XIAP (X-linked inhibitor of apoptosis)
Diseases named in the same sentence as XIAP in open-access papers (continued):
Sharing a sentence is not in itself a finding about the gene and the disease.
breast carcinoma (continued). "In breast cancer, aggressive B-cell lymphoma and glioblastoma, USP9X alleviates tumor cell survival and confers chemoresistance through YAP1, XIAP or Mcl-1 stabilization." (PMID 40246814, 2025). "Co-treatment with TNF-α and DEX effectively blocked TNF-α-induced apoptosis by inhibiting XIAP, c-IAP1, and c-IAP2 cleavage in human breast cancer cells (MCF-7)." (PMID 37733709, 2023). "Another PROTAC tractable target is Rac Family Small GTPase 1 (RAC1), inducing chemoresistance of breast cancer, interacts with co-opted E3 ligases MDM2 and XIAP, and potentially novel E3 ligases, ITCH and SMURF2." (PMID 37845222, 2023). "SMAD3 BMPR2, XIAP, and ESR1 have also been proven to be regulated by OS in skin fibroblasts, vascular smooth-muscle cells, PC6.3 cells, and breast cancer." (PMID 35954205, 2022). "In breast cancer cell lines, Survivin, as well as FOXM1 and XIAP have been shown to contribute to drug-resistance." (PMID 35331169, 2022). "The 3’UTR of XIAP can also function as a ceRNA, and decreased miR-29a-5p adsorbed FSCN1 increased motility of breast cancer cells." (PMID 35992856, 2022). "Ceramide analog LCL85 targeting XIAP and CIAP1 overcomes apoptosis-induced resistance in metastatic colon and breast cancer, thereby inhibiting metastasis in vivo." (PMID 35992856, 2022). "In breast cancer, CUDC-907 enhances TRAIL-induced apoptosis through the upregulation of cell survival proteins, including XIAP, Bcl-xL, and Bcl-2." (PMID 35205815, 2022). "In this study, the downregulation of XIAP and activation of caspase cascades in BT-474 cells by PTXNR-TTZ has proven to be an effective approach for the treatment of HER2 positive breast cancer cells." (PMID 33795712, 2021). "Our recent trends in the identification of regulated proteins by the critical genes in breast cancer cell progression such as PTTG1 and FOXO, resulted in a proliferation of studies that have led to a renewed interest in XIAP." (PMID 32537125, 2020). "XIAP, working as a bridge, links MAPK signaling and NF-κB hyperactivation, facilitating breast cancer progression." (PMID 33138314, 2020). "This study showed that HCT116 colon cells stably overexpressing XIAP WT displayed greater changes in OGT and O-GlcNAc modification levels than A549 lung cancer cells and MDA-MB231 breast cancer cells." (PMID 32994395, 2020). "The 3′-UTR of XIAP itself functions as ceRNA (competing endogenous RNA) and thus, frees FSCN1 from miR-29a-5p, which increases the motility of cells in breast cancer." (PMID 33138314, 2020). "Inhibitor of apoptosis proteins or IAPs (XIAP and BIRC2), and NOTCH signaling proteins are known to be involved in anti-apoptosis process and are elevated in many cancer cells, especially breast cancer." (PMID 30513116, 2018). "We examined the effect of NCTD on the expression of a panel of critical apoptosis-related proteins, including c-FLIP, XIAP, c-IAP-1, Survivin, Mcl-1, Bcl-xl and Bad, in these breast cancer cell lines." (PMID 28460471, 2017). "To confirm how XIAP 3′UTR affected the miRNA expression in vitro, we first detected the expression of miR-29a-5p in breast cancer cell lines and found that it was significantly lower than that the normal HMEC cells." (PMID 28186968, 2017). "To further verify this finding, we then chose a normal human mammary epithelial cell line (HMEC) and five breast cancer lines (MCF-7, MDA-MB-231, BT549, SKBR3 and T47D) to assess the roles of XIAP 3′UTR using qRT-PCR." (PMID 28186968, 2017).
breast carcinoma (continued). "In this study, we initially detected XIAP expression under the condition of serum-free vs. serum-containing and found that the levels between XIAP mRNA and protein were lack of correlation in breast cancer cells, which prompted us to explore the mechanisms underlying of XIAP mRNA regulation." (PMID 28186968, 2017). "Our data suggested that a positive correlation existed between the expression of XIAP 3′UTR and some EMT features, which likely contribute to the observed aggravation of tumor invasion and metastasis of breast cancer." (PMID 28186968, 2017). "SAHA decreased survivin and XIAP gene transcription, induced survivin protein acetylation and early nuclear translocation in MCF7 and MDA-MB-231 breast cancer cells." (PMID 27065869, 2016). "We also found that SAHA down-regulated survivin and XIAP expression in both MCF7 and MDA-MB-231 breast cancer cells." (PMID 27065869, 2016). "Then, we evaluated the impact of the expression of survivin and XIAP on the effectiveness of SAHA in reducing cell viability and up-regulating autophagy in breast cancer cells." (PMID 27065869, 2016). "Recently it has been reported that chemotherapy induced enhanced XIAP expression, partially mediated through PI3K/Akt signalling, resulting in chemo resistance in breast cancer cells." (PMID 26071313, 2015). "Micro-RNA profiling revealed upregulation of XIAP-targeting miR513a-3p in CFM-4-treated NB, mesothelioma, and breast cancer cells." (PMID 25033461, 2014). "TNF-α, when combined with WA or Cel, activated caspase-3 and -9 and downregulated XIAP in a dose-dependent manner, leading to induction of apoptosis in MDA-MB-231 breast cancer cells." (PMID 25419573, 2014). "In this respect, Xu and colleagues recently reported that significantly higher levels of XIAP are detected in breast cancer tissue versus normal breast tissue, but they could not confirm a correlation between XIAP expression, disease-free survival, and overall survival of breast cancer patients." (PMID 25120954, 2014). "In support of this, knockdown of XIAP, a related member of the BIRC-3 anti-apoptotic family in MCF-7 breast cancer cells sensitized these cells to apoptosis mediated by chemotherapeutic drugs." (PMID 21283672, 2011). "For instance, overexpression of XIAP and Survivin, another member of IAP family, resulted in severe resistance to Adriamycin, Paclitaxel and Vincristine in several kinds of breast cancer cell." (PMID 21645409, 2011). "It had been introduced previously that XIAP and Survivin, two important caspase inhibitors of IAP family, were comitantly overexpressing in several kinds of breast cancer cell and oweing to elevated resistance to chemotherapeutics." (PMID 21645409, 2011). "XIAP, c-IAP1 and c-IAP2 were chosen for subsequent analysis because they have roles in breast cancer progression." (PMID 20584313, 2010). "As with previous studies in the breast cancer cell lines and in the National Cancer Institute (NCI) panel of tumour cell lines, we found that XIAP expression was variable." (PMID 19563669, 2009). "We used small interfering RNA's (siRNA) directed against XIAP in three cell-lines derived from bile-duct epithelia (BDE), mammary carcinoma (P114), and osteosarcoma (D17)." (PMID 16953886, 2006). "This study evaluates the correlations between XIAP expression and clinicopathological features, including disease-free survival (DFS) and pathological complete response (pCR) to chemotherapy, in more than 2300 invasive primary breast cancer samples." (PMID 34199946, 2021). "Reducing expression of antiapoptotic regulators such as cIAP 1, Bcl-2, catalase,clusterin, HO-1, livin, XIAP, HSP27 and claspin was also demonstrated in human breast cancer line; the latter in support of mithochondrial apoptotic pathway using bromelain-based CHCT." (PMID 34466585, 2020).
breast carcinoma (continued). "Because CompA and birinapant are structurally similar, but have different affinities to the IAPs, we evaluated expression of their targets cIAP1, cIAP2, and XIAP in ER+ and TNBC PDX tumors to understand the differential responsiveness of the breast cancer subtypes to Smac mimetics." (PMID 32341449, 2020). "Aggressive breast cancer is mainly regulated by the MNK/XIAP/NF-κB axis, MNK (MAPK iNteracting Kinase) activation increases the XIAP protein, facilitating the interaction between BIR1 domain and TAB1 (TGFβ-associated binding protein) together with its cognate kinase TAK1." (PMID 33138314, 2020). "Our current data further strengthen this conclusion, as XIAP is downregulated by ONC201 in breast cancer cells even in the absence of apoptosis induction." (PMID 33144917, 2020). "In breast cancer cells in vitro, BITC induced apoptosis via suppression of XIAP expression." (PMID 30970087, 2019). "For example, breast cancer cell lines harboring DNM1L amplifications exhibited hypersensitivity to the ER stress-inducing drug thapsigargin and the XIAP inhibitor embelin as well as resistance to chemically distinct inhibitors of the phosphoinositide 3-kinase (PI3K) pathway." (PMID 29700304, 2018). "On the basis of our clinico-pathological observations, we hypothesized that co-targeting of both PARP and XIAP might be an affective therapeutic target in treating aggressive BC and might extend the utility of olaparib beyond BRCA mutant breast cancer patients." (PMID 30647872, 2018). "Herein, suppression of breast cancer cell apoptosis by miR-23a is probably mediated by some other genes rather than XIAP." (PMID 29113338, 2017). "A number of XIAP antagonists with nanomolar affinity to the baculovirus IAP repeat 3 (BIR3) domain of XIAP have been described which promote apoptosis in resistance cancer cell lines and inhibit the growth of tumors in a MDA-MB-231 breast cancer mouse xenograft model." (PMID 27923354, 2016). "BRE expression has been shown to be predictive of disease free survival in non-familial breast cancer patients and recent studies show its involvement in both intrinsic and extrinsic apoptotic pathways by influencing XIAP." (PMID 27047539, 2016). "Surprisingly, ectopic over-expression of XIAP only attenuated the cell viability inhibitory effect of SAHA in MCF7 but not in MDA-MB-231 breast cancer cells." (PMID 27065869, 2016). "As EVO has been reported to inhibit the expression of IAPs, such as XIAP, survivin and cIAP1, and to modulate ERK signaling, we hypothesized that EVO could reverse DOX-resistant breast cancer cells by inhibiting the Ras/MEK/ERK pathway and IAPs." (PMID 24830744, 2014). "In previous studies, CuE (1–10 μM) inhibited the pSTAT3 and induced apoptosis in human breast cancer cell lines Bcap37 and MDA-MB-231 and decreased the levels of the anti-apoptotic proteins XIAP, Survivin, and Mcl-1, and increased the level of Bax in human leukemia HL-60 cells." (PMID 25072848, 2014). "In a breast cancer cell line overexpressing ErbB2, embelin alone decreased the viability of cells (tetrazolium), although siRNA to XIAP did not." (PMID 24603802, 2014). "For example, cisplatin treatment of prostate cancer cells resulted in upregulation of Survivin, XIAP and cIAP2; adriamycin-resistant MCF7 breast cancer cells showed upregulation of XIAP and Survivin; and Lapatinib-resistant BT474 breast cancer cells had elevated Survivin levels." (PMID 25328816, 2013). "Preliminary research showed positive ratio of XIAP in breast cancer were 89.7%, but no related report about Smac." (PMID 21645409, 2011). "XIAP siRNA enhances sensitivity to methotrexate in hepatoma, to cisplatin, fluorouracil and etoposide in oesophageal carcinoma, to TRAIL in melanoma, breast cancer and pancreatic cancer and also sensitises pancreatic cancer cell lines to γ-irradiation." (PMID 19904270, 2010).
breast carcinoma (continued). "Interestingly, XIAP knock-down restored TRAIL sensitivity in Me1007 and this was not cell-type specific because a similar phenomenon was observed in the mammary carcinoma cell line MDA-MB231." (PMID 20461078, 2010). "Since XIAP is the most potent caspase inhibitor in the IAP family, we determined whether it contributed to the apoptotic resistance of breast cancer cells using RNAi." (PMID 19563669, 2009). "However, in breast cancer cells it was found that knockdown of RPS3 downregulated cellular levels of XIAP at the protein level but not at the mRNA level." (PMID 40940922, 2025). "However, the characterization of XIAP expression in relation to clinicopathological variables in large clinical series of breast cancer is lacking." (PMID 34199946, 2021). "Further, as pCR is associated with favorable disease-free and overall survival in early-stage breast cancer, limiting the negative impact of XIAP during neoadjuvant therapy may result in important gains in efficacy." (PMID 34199946, 2021). "Moreover, RQ-PCR analysis revealed that the enhanced cytotoxic effect of As2O3 in the presence of melatonin is mediated, at least partly, through suppressing the expression of NF-κB anti-apoptotic target genes such as MCL-1, BCL-2, survivin, XIAP, and c-IAP1 in breast cancer cells." (PMID 31565647, 2018). "Next, we found that overexpression of miR-489 decreased the expression of XIAP in breast cancer cells, no matter whether they were treated with 5-FU in vitro and in vivo." (PMID 29371950, 2017). "It suggested the negative correlation between miR-489 and XIAP in breast cancer." (PMID 29371950, 2017). "Taken together, it seems that induction of autophagy, at least as indirectly indicated by the increased conversion of LC3B-II, only occurred in breast cancer cells with survivin down-regulation but not with XIAP down-regulation following the knockdown of different HDAC isoforms by siRNA." (PMID 27065869, 2016). "Taken together, these results suggest that TNF-α could sensitize breast cancer cells MDA-MB-231 to WA and Cel, at least in part, through inhibiting the activation of NF-κB signaling, leading to XIAP inhibition with subsequent upregulation of caspase-3 and -9 activities." (PMID 25419573, 2014). "We have identified xIAP and cIAP1 as molecular targets of ceramide and determined that ceramide analog LCL85 is an effective sensitizer in overcoming resistance of human cell lines established from metastatic colon and breast cancers to apoptosis induction to suppress metastasis in vivo." (PMID 24422988, 2014). "However, we are the first to establish whether antagonists of endogenous anti-apoptotic proteins, such as XIAP, can improve the efficacy of TAM targeted therapies and the possible role in Akt regulation, in breast cancer." (PMID 23613836, 2013). "Therefore, we concluded XIAP, like Survivin, probably was a new independent prognostic biomarker of breast cancer although it was different that only XIAP nuclear labeling, but not cytoplasm staining, had prognostic significance." (PMID 21645409, 2011). "However, the role of XIAP in breast cancer from Middle Eastern region has not been fully explored." (PMID 28893228, 2017). "Elevated expression of specific members of the IAP family may be tumor specific, as studies in breast cancer cells showed elevated expression of cIAP2, where other members of the IAP family (cIAP1 and XIAP) were not upregulated." (PMID 24708840, 2014). "Interestingly, its expression in both triple positive (MCF-7) and triple negative (MDA-MB-231) breast cancer cells were equal and higher than the non-tumorigenic mammary epithelial cells (MCF-10), have noted the impact of XIAP in proliferation of breast tumor cells." (PMID 32537125, 2020). "Therefore, unlike survivin, XIAP may only play a minor and also a cell line-dependent role in SAHA-induced autophagy and cell viability reduction in breast cancer cells." (PMID 27065869, 2016).
ovarian carcinoma (82 papers, 2007 to 2025). A malignant neoplasm originating from the surface ovarian epithelium. "Not only were ROS levels in SKVO3 ovarian cancer cells increased, but the expression of XIAP (X-linked inhibitor of apoptosis), cyclin D1, and BCL2 genes was reduced upon treatment with the triple combination, leading to increased cytotoxicity of SKOV-3 cells." (PMID 41226260, 2025). "Researchers have found that BRCA mutations lead to XIAP overexpression, making ovarian cancer sensitive to the IAP family." (PMID 38364254, 2024). "Cell lines and tissues associated with ovarian cancer, the level of XIAP protein is inversely linked with the expression of miR-137." (PMID 37222810, 2023). "miR-509-3p overexpression not only downregulates the expression of X-linked inhibitor of apoptosis protein (XIAP) in ovarian cancer cells, but also inhibits the proliferation of EOC cells and increases their sensitivity to cisplatin-induced apoptosis." (PMID 37386587, 2023). "Elevated IAP protein levels (XIAP, cIAP1, cIAP2 in particular) are common in many cancer types including ovarian cancer and this is one mechanism that underlies the resistance of cancer cells to apoptosis." (PMID 35501389, 2022). "As a result, the expression of XIAP has been linked to chemoresistance in established ovarian cancer cell lines and primary cultures." (PMID 36551731, 2022). "Emodin sensitized human ovarian cancer cells to the action of taxol, which was associated with the reduction of P-glycoprotein, XIAP, survivin levels and the induction of apoptosis." (PMID 35955645, 2022). "The clinicopathological significance of ATM, PTEN, p85α, and XIAP (X-linked inhibitor of apoptosis protein) was evaluated in 525 human ovarian cancers using immunohistochemistry." (PMID 31635307, 2019). "Martin and Ouchi, 2005 have shown that BRCA1 interacts with X-linked inhibitor of apoptosis protein (XIAP) in an ovarian carcinoma cell line SNU-251 and that the BRCA1-XIAP complex is disrupted by UV-induced phosphorylation of BRCA1." (PMID 30323899, 2018). "MiR-137 promoted apoptosis in ovarian cancer cells via targeting the X-linked inhibitor of apoptosis protein." (PMID 29016699, 2017). "Chemoresistance after cisplatin treatment is linked to enhanced expression of XIAP in ovarian carcinoma cells." (PMID 25120954, 2014). "In previous studies we have shown that resistance of ovarian cancer cells to Carboplatin is associated with high XIAP levels, and that this resistance can be reversed by pretreatment with Phenoxodiol, which causes XIAP degradation and ubiquitination." (PMID 17257402, 2007). "Phenoxodiol is an isoflavone derivative that has been shown to cause proteasomal degradation of XIAP, and reverse chemoresistance in ovarian cancer cells." (PMID 17257402, 2007). "MiR-519d-3p could repress ovarian cancer cell proliferation and promote cell death by targeting X-linked inhibitor of apoptosis protein (XIAP)." (PMID 25803859, 2015). "Phenoxodiol causes XIAP degradation and chemotherapy sensitization in ovarian cancer." (PMID 17257402, 2007). "In ovarian cancer, there is evidence demonstrating that the expression of XIAP not only regulates drug-induced apoptosis but also mediates chemoresistance." (PMID 38137377, 2023). "APG-1387, a smac mimetic, targets cIAP1, cIAP2, and XIAP, inducing autophagy and cell death in human ovarian cancer cells." (PMID 36358282, 2022). "It occurs coincidently with a recent study that miR-137 promotes apoptosis in ovarian cancer cells via downregulation of XIAP." (PMID 35965517, 2022). "Meanwhile, OTS514 dramatically inhibited the expression of p-IκBα, XIAP, and Bcl-XL in ovarian cancer cells." (PMID 35859118, 2022).